HYAL2 (hyaluronidase 2)
Diseases named in the same sentence as HYAL2 in open-access papers (continued):
Sharing a sentence is not in itself a finding about the gene and the disease.
cancer (47 papers, 2004 to 2025). A tumor composed of atypical neoplastic, often pleomorphic cells that invade other tissues. "High levels of PD-L1 are associated with immune suppression, whereas Hyal2 expression indicates the involvement of these cells in the process of HA degradation which contributes to cancer-related inflammation." (PMID 35528727, 2022). "Second, functional deficiency or defect of the HYAL-2-WWOX-SMAD4 signaling complex may occur in cancer cells." (PMID 27999774, 2016). "The Hyal-2/WWOX/Smad4 signaling induces spleen Hyal-2+ CD3- CD19- Z cell activation for eradicating cancer cells." (PMID 38542478, 2024). "The hyaluronidase 2 (HYAL2) is specifically expressed in endothelial cells and upregulated in different types of cancer." (PMID 38384845, 2024). "In particular, overexpression of Hyal-1 and Hyal-2 during cancer metastasis has been reported in many in vitro and in vivo studies, and it has recently been suggested that HA fragments promote cancer progression through Hippo-Yap signaling." (PMID 37328876, 2023). "Although all the designed drugs utilize the HYAL-2/WWOX/SMAD4 signaling to control cancer growth, it is necessary to compare the efficacy of HAson8, Zfra4-10, WWOX7-21 and other available drugs in treating cancer in vivo." (PMID 35883580, 2022). "Some of these AASEs affect genes that are not only associated with immunity but also play essential roles in inflammation (e.g., FN1 and HYAL2) and cancer oncogenesis (e.g., CTTN, FN1, and DGKZ)." (PMID 35752626, 2022). "Reduced expression of Hyal-2 and Zfra in the spleen suggests that activated memory Z cells participate in cancer suppression by relocating to the cancer lesions." (PMID 32764489, 2020). "Hypothetically, Zfra4-10 binds to the membrane Hyal-2 of spleen Z cells and activates the Hyal-2/WWOX/SMAD4 signaling for cytotoxic Z cell activation to kill cancer cells." (PMID 32764489, 2020). "Similar to connective tissue homeostasis and cancer metastasis, Hyal-2 OEx by trophoblast cells induced both zymogen as well the mature form of MMP-9 in a similar pattern to that previously demonstrated in vitro." (PMID 33208556, 2020). "In particular, the over-expression of Hyal-1 and Hyal-2 was reported during cancer metastasis in many in vitro and in vivo studies and recently it was suggested that HA fragments promote cancer progression via Hippo-Yap signaling." (PMID 32708202, 2020). "Taken together, sonicated HA and specific antibodies against Hyal-2 act as agonists in stimulating membrane Hyal-2 in Z cells, so as to suppress cancer growth." (PMID 32764489, 2020). "These peptides probably utilize the Hyal-2/WWOX/Smad4 signaling to exert cancer growth suppression and assist ceritinib-mediated enhancement of cancer cell death." (PMID 31752354, 2019). "WWOX7-21 and WWOX7-11 peptides probably drive the Hyal-2/WWOX/Smad4 signaling for cancer suppression by binding with membrane WWOX and/or Hyal-2." (PMID 31752354, 2019). "Inhibition of Hyal-2 by specific antibody against Hyal-2 or pY216-Hyal-2 leads to cancer growth suppression and prevention in vivo." (PMID 31752354, 2019). "We also reported that treatment of cancer cells with Hyal-2 or pY216-Hyal-2 antibody results in suppression of cancer growth in vivo." (PMID 31752354, 2019). "We determined that inhibition of membrane hyaluronidase Tyr216-phosphorylated Hyal-2 by antibody suppresses cancer growth in vivo." (PMID 31123603, 2019). "In the existing of Hyal-2 that is overexpressed in the intracellular compartments of cancer cells, the HANP was disrupted and 85.84 ± 7.46% of HCPT was released in 8 hours." (PMID 29097925, 2017). "HYAL2-var2 mRNA was more highly expressed in solid metastases compared to effusions and primary carcinomas, whereas the opposite was true for HYAL3-var1-3." (PMID 23202930, 2012). "Similar trend was noticed between HYAL2 expression in grade 1 and grade 2 + 3 cancers compared to normal endometrium, this difference being borderline significant." (PMID 20875124, 2010).
cancer (continued). "Allelic imbalance is frequent in the 3p21.3 chromosome region containing HYAL1 and HYAL2 genes, suggesting that this site is important in ovarian and other cancers." (PMID 19435493, 2009). "An increase of HYAL2 expression occurred in benign tumors compared to normal ovaries (+76%, P = 0.037), and while a decrease was noted in grade 3 cancers compared to benign tumors (P = 0.0156)." (PMID 19435493, 2009). "In addition, 8-h-sonicated hyaluronan (HAson8) and antibody against Hyal-2 or pY216-Hyal-2 activate Z cells to kill cancer cells." (PMID 38542478, 2024). "Thus, Zfra4-10 and WWOX7-21 peptides, HAson8, and HYAL-2 antibodies are of therapeutic potential for cancer suppression." (PMID 35883580, 2022). "Whether the HYAL-2/WWOX/SMAD4 signaling limits cancer and neurodegeneration in a balanced manner is unknown." (PMID 35883580, 2022). "Additionally, Zfra4-10 blocks NF-κB-mediated inflammation and accelerates degradation of proteins in the AD pathologies, as well as induction of the activation of HYAL-2+ CD3− CD19− lymphocytes to kill cancer in vivo." (PMID 35883580, 2022). "Finally, stimulating the membrane HYAL-2/WWOX complex with HYAL-2 antibody or sonicated hyaluronan (HAson) leads to Z cell activation for killing cancer cells in vivo and in vitro." (PMID 35883580, 2022). "In our model, exon 2 of HYAL2 exhibited a higher inclusion ratio in WASP-KO-iMPs, which might be related to the high cancer susceptibility in WAS patients." (PMID 35752626, 2022). "Indeed, antibodies against pY33-WWOX and Zfra4-10 peptide are potent in blocking cancer growth, suggesting that the Hyal-2/WWOX signaling is functioning in the anticancer response." (PMID 32764489, 2020). "Thus, Zfra4-10 and WWOX7-21 peptides, HAson, and the Hyal-2 antibody are of therapeutic potential for cancer suppression." (PMID 32764489, 2020). "Some reports show that the expression of HYAL1 and HYAL2 depends highly on the cancer type." (PMID 32610620, 2020). "We investigated whether synthetic Zfra4-10 or WWOX7-21 peptide-mediated cancer suppression occurs via the Hyal-2/WWOX/SMAD4 signaling for cytotoxic memory Z cell activation in the spleen." (PMID 32764489, 2020). "Zfra activates memory spleen cells for cancer targeting via interacting with membrane HYAL-2." (PMID 27999774, 2016). "In contrast, HYAL2-var2 was detected in 14/51 (27%) effusions, 4/25 (16%) primary OC and 9/9 (100%) solid metastases, with significantly higher expression in solid metastases compared to effusions and primary carcinomas (p < 0.001)." (PMID 23202930, 2012). "HYAL1 mRNA was absent in all specimens, whereas HYAL2 was expressed as two splice variants, of which HYAL2-var2 was overexpressed in solid metastases compared to effusions and primary carcinomas (p < 0.001)." (PMID 23202930, 2012). "Hyal-1 and Hyal-2 were overexpressed in cancerous samples, especially in advanced stages of cancer." (PMID 20849597, 2010). "HYAL2 mRNA was also reduced in cancer (p = 0.02) and correlated with HYAL1 (r = 0.8, p = 0.0001)." (PMID 20875124, 2010). "In contrast, under-expression of HYAL-1 and HYAL-2 may contribute to poorer prognosis in pancreatic, ovarian, and endometrial malignancies, suggesting that the detrimental effects of hyaluronidases in cancer might vary depending on the type of cancer." (PMID 36613567, 2022). "Thus, suppression of Hyal-2 by antibody limits cancer growth." (PMID 31123603, 2019). "The mechanisms of cancer-related aberrant HYAL2 methylation in blood remain unknown." (PMID 28978057, 2017). "Thus analysis of HYAL1 and HYAL2 can have a great importance not only for better understanding of HA catabolism and human carcinogenesis but could provide therapeutic targets for cancer treatment." (PMID 18725949, 2008). "It is particularly important to understand the two pathways of HA degradation in malignant tumors, one involving HAYL1/HYAL2 and the other CEMIP/CEMIP2." (PMID 39858106, 2025).
cancer (continued). "Both peptides probably mediate the signaling from membrane Hyal-2/WWOX and then recruit Smad4 for blocking cancer growth." (PMID 38542478, 2024). "Zfra-activated Hyal-2+ CD3- CD19- Z cells in the spleen, via Hyal-2/WWOX/Smad4 signaling, are potent in cancer suppression." (PMID 38542478, 2024). "Agonist Zfra4-10 or WWOX7-21 peptide, HYAL-2 antibody or sonicated hyaluronan HAson8, also activate the HYAL-2/WWOX/SMAD4 signaling for spleen Z cell activation in order to kill cancer cells in vitro and in vivo." (PMID 35883580, 2022). "The top ten from the univariable analyses for the cancer versus cancer-free comparison composed of two miRNAs (409 and 200c) and 8 CpG sites (4 CpGs at SLC22A18, 3 at HYAL2, and 1 at FUT7)." (PMID 35284957, 2022). "The stronger the binding, the weaker the cancer growth, suggesting that Zfra4-10 or WWOX7-21 peptide-induced HYAL-2/WWOX/SMAD4 signaling is involved in the increased binding of WWOX with its partners." (PMID 35883580, 2022). "Hyaluronidase hydrolases that are responsible for the degradation of HA to its LMW form were upregulated by hypoxia in cancer cells, and LAD2 MCs express a member of the hyaluronidase hydrolase family HYAL2." (PMID 34791576, 2022). "The activated Z cell, which is HYAL-2+ CD3− CD19−, is highly potent in killing cancer cells both in vitro and in vivo." (PMID 35883580, 2022). "Previously, it has been shown that highly invasive cancer cell lines like the MDA-MB-231 have a high expression of HAS2 mRNA and also HYAL2, resulting in higher turnover and accumulation of HA with low molecular weight." (PMID 32824576, 2020). "This raises the strong scenario that both peptides drive a common signal pathway, which is Hyal-2/WWOX/SMAD4, to limit cancer growth." (PMID 32764489, 2020). "Indeed, the roles of HYAL1 and HYAL2 in cancer progression may vary depending on the cancer type." (PMID 33171800, 2020). "How Zfra utilizes the Hyal-2/WWOX signaling to enable Z cells to recognize and kill cancer cells is very intriguing and remains to be established." (PMID 32764489, 2020). "Peptides or monoclonal antibodies are being developed to target membrane Hyal-2 as well as WWOX and to activate Z cells in blocking cancer and neurodegeneration." (PMID 30158849, 2018). "High molecular weight HA increases the formation of endogenous Hyal-2/WWOX/Smad4 complex rapidly, followed by relocating to the nuclei in 20-40 min, in WWOX-expressing normal and cancer cells." (PMID 27845895, 2017). "Clearly, the Hyal-2+ CD3− CD19− Z cell lineage is an effector memory system, which can be educated for eradicating cancer cells." (PMID 25686832, 2015). "In addition, an increased number of HA-containing HYAL2+PD-L1+ myeloid-derived suppressor cells (MDSCs) have been observed in ccRCC, promoting HA degradation to LMW-HA, cancer-related inflammation, and immunosuppression." (PMID 38724670, 2024). "In this perspective review article, we detail the molecular action of WWOX in the HYAL-2/WWOX/SMAD4 signaling for biological effects, and discuss WWOX phosphorylation forms in interacting with binding partners, leading to suppression of cancer growth and retardation of AD progression." (PMID 35883580, 2022). "When cancer cells are transiently overexpressed with SMAD4, WWOX and HYAL-2, HA induces cell death." (PMID 35883580, 2022). "Nonetheless, UV-generated HA fragments are not effective in blocking cancer growth, suggesting that the Hyal-2/WWOX pathway is not activated in Z cells." (PMID 32764489, 2020). "Finally, we developed Zfra4-10 and WWOX7-21 peptides, sonicated hyaluronan HAson, and Hyal-2 and pY33-WWOX antibodies as therapeutic drugs for cancer treatment." (PMID 32764489, 2020). "In addition to Zfra4-10 and WWOX7-21 peptides, stimulating the membrane Hyal-2/WWOX complex with Hyal-2 antibody and sonicated hyaluronan (HAson) induced Z cell activation for killing cancer cells in vivo and in vitro." (PMID 32764489, 2020).
cancer (continued). "For example, WWOX7-21 peptide may physically bind the membrane Hyal-2/WWOX complex to undergo nuclear relocation, together with Smad4, for blocking cancer cell growth." (PMID 31752354, 2019). "Indeed, high-molecular-weight native HA promotes cancer growth, suggesting that its binding and the agonizing effect for membrane Hyal-2 are probably not strong enough." (PMID 32764489, 2020). "In addition, a small synthetic peptide Zfra (zinc finger-like protein that regulates apoptosis) binds membrane HYAL-2 of non-T/non-B spleen HYAL-2+ CD3− CD19− Z lymphocytes and activates the cells to generate memory anticancer response against many types of cancer cells in vivo." (PMID 27999774, 2016).
infection (10 papers, 2005 to 2024). The state of being infected such as from the introduction of a foreign agent such as serum, vaccine, antigenic substance or organism. "For instance, hyaluronidase-2 was expressed at a relative higher level in resistant fish than in susceptible fish before infection, and it was induced more in susceptible fish than resistant fish after infection." (PMID 25888203, 2015). "In up-regulated genes of head kidney samples, 2 genes respond to infection by D. pseudospathaceum-clone I (HYAL2, PRF1), 3 to clone XII (RGCC, CYP27B1, CCR9) and 6 to the clone mix treatment (ITGA5, SIX1, ATP1B3, MEF2C, MLF1, MYLPF)." (PMID 25254967, 2014). "HYAL2 is expressed at the cell surface and mediates infection by retroviral vectors pseudotyped with the JSRV or ENTV envelope proteins." (PMID 22655078, 2012). "Through the transduction and infection of lung and nasal turbinate tissue slices, we observed that Hyal2 expression levels strongly influence ENTV entry, but that the long terminal repeat (LTR) promoters of these viruses are likely responsible for tissue-specificity." (PMID 31739606, 2019). "Indeed, our results would suggest that in the case of ENTV, an endogenous threshold of Hyal2 seems to act as the primary block to infection in the lung." (PMID 31739606, 2019). "In contrast, the genes encoding hyaluronoglucosaminidases (HYAL1, HYAL2), the enzymes that degrade HA, were repressed, indicating that perhaps HA is not degraded during a B. pseudomallei infection." (PMID 21110886, 2010). "To study the role of hyaluronan at the feto-maternal interface during the postimplantation period, we used lentiviral infection to generate blastocysts expressing EGFP in their trophectoderm cells, along with overexpression of Hyal-2." (PMID 33208556, 2020). "Evidence for Hyal2 function as the virus receptor is provided by experiments showing that expression of sheep or human Hyal2 in cells that are not normally susceptible to infection renders the cells fully infectable by retroviral vectors bearing the JSRV or ENTV Env proteins." (PMID 16191204, 2005). "We show that the greatly reduced receptor activity of mouse Hyal2 in comparison to that of human Hyal2 is determined by multiple amino acid changes acting in concert, and that no one amino acid change blocks infection." (PMID 16191204, 2005). "Infection by jaagsiekte sheep retrovirus (JSRV) and by enzootic nasal tumor virus (ENTV) depends on cell-surface expression of the virus entry receptor, hyaluronidase 2 (Hyal2)." (PMID 16191204, 2005).
genetic disorders (1 paper, 2024). "Of these, only deficiencies in HYAL1, HYAL2, HYAL3 and CEMIP have been identified as the cause or putative cause of human genetic disorders." (PMID 39056785, 2024).
malformation syndrome (1 paper, 2017). "With the Hyal2-/- mouse model already available, testing of such strategies may enable the development of a pre-natal treatment for this malformation syndrome." (PMID 28081210, 2017).
neurological disease (1 paper, 2019). "SFN is located at the center of an interaction network of proteins including HYAL2, NBEA, NBR1, AURKAIP1, RALGPS2, and SLC1A2, some of which have known involvement in brain function and neurological disease." (PMID 31029150, 2019).
HYAL2 also shares sentences with these, for which no sentence is quoted: Alzheimer disease (2 papers); colitis (2); benign tumors (1); COVID-19 (1); developmental delay (1); endothelial dysfunction (1); gastrointestinal disorders (1); idiopathic pulmonary fibrosis (1); invasive breast carcinoma (1); keloid (1); lung adenocarcinoma (1); malignant pleural mesothelioma (1); metastatic melanoma (1); microcephaly (1); mitral valve atresia (1); myopia (1); neuroblastoma (1); non-small cell lung carcinoma (1); Obesity (1); optic atrophy (1); osteoporosis (1); renal cell carcinoma (1); rheumatoid arthritis (1); spastic ataxia (1); triple-negative breast carcinoma (1); virus infection (1); ZIKV infection (1).